QSOX1 (quiescin sulfhydryl oxidase 1)
Diseases named in the same sentence as QSOX1 in open-access papers (continued):
Sharing a sentence is not in itself a finding about the gene and the disease.
cancer (continued). "While further research is still needed to understand the role of QSOX1 in vivo, the results presented here strongly suggest that targeted inhibition of QSOX1 may stall cancer progression." (PMID 23536962, 2013). "In fact, QSOX1 expression is differentially modulated in some cancers." (PMID 23098186, 2012). "The differential localization of QSOX1 in normal and cancer cells could be due to post-translational modifications and/or a differential regulation of the expression of QSOX1 isoforms." (PMID 23098186, 2012). "Similarly, sulfhydryl oxidase 1 (QSOX1) has been intensively studied in relation to cancer." (PMID 34770976, 2021). "QSOX1, whose functions include formation of disulphide bridges, which are needed for correct protein folding and stability, formation of the extracellular matrix, regulation of the redox status and cell cycle control, appears to be involved in apoptosis in pathological states such as cancer." (PMID 25908093, 2015). "Specifically, the disulfide bond-forming activity of the enzyme Quiescin sulfhydryl oxidase 1 (QSOX1) is required by fibroblasts to assemble ECM components for adhesion and migration of cancer cells." (PMID 32064042, 2020). "Quiescin Sulfhydryl Oxidase 1 (QSOX1), a flavo-enzyme involved in oxidative protein folding, has been correlated with cell invasion, proliferation, and poor prognosis in pancreatic, prostate, and breast cancers." (PMID 39518060, 2024). "Three selected proteins (QSOX1, THBS1 and EDIL3) were detected in CRC patient pEXOs and might be useful candidates in early cancer diagnostics engaging non-invasive liquid biopsy." (PMID 33802764, 2021). "Vertebrate QSOX1 can be cleaved from its transmembrane domain to allow secretion, and has been shown in vitro to be required extracellularly for the incorporation of laminin produced by fibroblasts into the extracellular matrix (ECM), thereby supporting efficient cancer cell migration." (PMID 30910009, 2019). "The mammalian ortholog QSOX1 has been shown to affect disulfide bond formation, is overexpressed in some cancers, promotes Matrigel invasion, and can serve as a negative prognostic indicator in human cancer patients." (PMID 30910009, 2019).
cardiac disease (1 paper, 2022). "However, the Boruta algorithm identified some important additional biomarkers, for example, quiescin sulfhydryl oxidase 1 (O00391), a known marker of cardiac disease, that LASSO regression did not detect." (PMID 35317720, 2022).
QSOX1 also shares sentences with these, for which no sentence is quoted: non-small cell lung carcinoma (2 papers); adenocarcinoma (1); breast adenocarcinoma (1); colon cancer (1); endothelial dysfunction (1); infection (1); intraepithelial neoplasia (1); liver disease (1); liver fibrosis (1); lung adenocarcinoma (1); pancreatic adenocarcinoma (1); prostatic hyperplasia (1); prostatic intraepithelial neoplasia (1).